ERBB2 (erb-b2 receptor tyrosine kinase 2)
Diseases named in the same sentence as ERBB2 in open-access papers (continued):
Sharing a sentence is not in itself a finding about the gene and the disease.
cancer (continued). "As a result, ERBB2 CNG may be discovered by NGS testing but its correlation with standard HER2 testing by IHC for overexpression or FISH for amplification, which have been validated in breast and GEA cancers to predict benefit from HER2-therapy, is less well understood." (PMID 35126865, 2022). "Moreover, brain-seeding clones acquire early clonal divergence from primary clones with increased numbers of distinct alterations in PI3K, EGFR, ErbB2 (HER2), ALK, Wnt/b-catenin and EMT signaling pathways, which seems to be crucial in spreading of cancers to the brain." (PMID 35406585, 2022). "Since more than 75% of ERBB2 fusions were accompanied by ERBB2 amplification, we also analyzed the difference in CNV values between the pure ERBB2 amplification (ERBB2 Amp) and ERBB2 amplification combined with fusion (ERBB2 Fusion + Amp) in different cancer types." (PMID 36276102, 2022). "Eight studies performed sequencing through different cancer‐related gene panels, and nine studies sequenced only predesignated genes including EGFR, KRAS proto‐oncogene (KRAS), B‐Raf proto‐oncogene (BRAF), erb‐b2 receptor tyrosine kinase 2 (ERBB2), and MET proto‐oncogene (MET)." (PMID 36000927, 2022). "We could not rigorously evaluate ERBB2 status by reproductive category due to the lack of ERBB2 clinical data for most patients in the Utah Cancer Registry." (PMID 36239933, 2022). "Such cancers might be very sensitive to inhibition of ERBB2-ERBB3, and there are several recent reports of good responses in patients to anti-ERBB2 or anti-ERBB3 therapy, including anti-ERBB3 antibody and HER-family kinase inhibitors such as the pan-ERBB inhibitor afatinib." (PMID 33413557, 2021). "Most women for whom neoadjuvant treatment is indicated receive chemotherapy, although endocrine therapy may be offered as an alternative for some women with strongly HR-positive and ERBB2-negative cancer." (PMID 33710293, 2021). "ERBB2 is a vital cancer marker, and no ligand for ERBB2 has been found yet." (PMID 33732282, 2021). "Because all these processes are critical for cancer progression, our observation warrants further research on the molecular mechanisms that mediate this Tz effect and possible functional implications of the inclusion of CD63 50 kDa isoform in exosomes released by ERBB2+ BCa cells." (PMID 33809102, 2021). "Moreover, Her2e has a distinctive profile independent of ERBB2 amplification, suggesting its relevance even in cancers lacking ERBB2 enrichment." (PMID 33396205, 2020). "Finally, the ERBB2-amplified cancers represent a separate subgroup with negative prognosis and they are composed of HER2-enriched (ER-negative) cases and luminal (ER-positive) cases." (PMID 32210163, 2020). "The top 15 SGA-FIs connected with CSMD3 and ZFHX4 also form densely connected networks that include well-known cancer drivers, such as KRAS, GATA3, KEAP1, ERBB2 and STK11, suggesting that alteration of CSMD3 and ZFHX4 may perturb some of the same signaling pathways as do these known drivers." (PMID 31276486, 2019). "Notch, ERBB2, and FGFR1 signaling pathway might be potential therapeutic targets to improve the outcome of CRC patients without germline cancer-associated genetic variants in adjuvant setting." (PMID 30850667, 2019). "In contrast, proteins that promote various cancer malignant properties, including CCND1, ERBB2, SNAIL, SLUG, phosphorylated STAT3 (p-STAT3), FAK, FOXM1, ETS1, YAP, HES1, and OCT4, were all significantly downregulated, an indication of reduction of malignancy in the cancer cells after EZH2 knockdown." (PMID 31130994, 2019). "Moreover, mutations of FBWX7, ERBB2, TET2, BCL2L1, NOTCH1, FGFR1 and TSC1 were only detected in patients without germline cancer-associated variants." (PMID 30850667, 2019).
cancer (continued). "In conclusion, we show PHLDA2 regulation by EGFR/ErbB2 signaling, demonstrate a correlation between PHLDA2 expression, AKT pathway activation and EGFR mutational status and show that PHLDA2 has key negative feedback inhibitory functions in EGFR/ErbB2-driven cancer cells." (PMID 29861842, 2018). "Importantly, to further evaluate the impact of ganetespib-mediated ErbB2-targeting function, we compared the cellular sensitivity of paired isogenic cancer cell lines with/without ErbB2 overexpression." (PMID 29717218, 2018). "HER2 (ErbB2 or HER-2/neu) belongs to the human epidermal growth factor receptor (HER) family and is significantly correlated with the proliferation, migration, and differentiation of many kinds of cancer cells through its involvement in the activation of the PI3K/Akt and Ras/Raf/MEK/MAPK pathways." (PMID 28977908, 2017). "While studies have shown how type I classical cadherin fragments can mediate this process in cancer cells, our data show how the shed fragment of the type II classical cadherin, cadherin-11, can promote this process in CNC cells by interacting with ErbB2 to increase Akt activity." (PMID 29190819, 2017). "Therefore, it is possible alcohol regulates cancer stemness by activating EGFR and ErbB2." (PMID 29156633, 2017). "The ERBB2 cell surface antigen is an excellent target in CAR-T technology as the extracellular domain of the receptor could easily be subjected to the antibody binding mechanism and is currently used as a potential target in cancer vaccine trials." (PMID 28885562, 2017). "Indeed, overexpression of miRNA-7 in cells shows significant downregulation of ERBB2 but not EGFR1 in contrast to EGFR being targeted by miRNA 7 in cancer cells suggesting cell specific regulation of miRNA targeting the EGFR receptors." (PMID 28329018, 2017). "Furthermore, since PI3K integrates both the ErbB2/Grb2/SOS/RAS and ErbB3/p85 pathway, the ErbB2-overexpressing cancer cells become addicted to the PI3K signalling hub, as manifested by increased susceptibility to PI3K inhibitors, compared with ErbB3 inhibition." (PMID 27255951, 2016). "It is not known why TOM1L1 is not tyrosine-phosphorylated in ERBB2-positive cancer cells." (PMID 26899482, 2016). "Therefore, in addition to ErbB2/HER2, p38γ MAPK may be a potential target for the treatment of alcohol-enhanced cancer aggressiveness." (PMID 27416801, 2016). "AT1 receptor is expressed in several human cancer cell lines including pancreatic and prostate cancer cell lines and in a subpopulation of ER-positive, ERBB2-negative breast cancer cases, and ARB treatment suppressed AT1 receptor-positive cancer cell proliferation and tumor growth." (PMID 29259685, 2016). "However, HER2-positive cancers, which showed amplification and overexpression of the ERBB2 gene, did not express hormone receptors and thus represented a poor prognosis." (PMID 25908947, 2015). "One important ErbB2-activated, invasion-promoting group of signaling proteins is the p21-activated protein kinase (PAK) family of serine/threonine kinases that function as effectors of Cdc42 and Rac and are involved in cytoskeletal organization and cancer cell invasion in general." (PMID 24709902, 2014). "Therefore, we did not consider ErbB2 in the cytoplasm and nuclei of cancer cells as positive; rather, we determined pErbB2 in the cytoplasm and nuclei of these cells to be positive." (PMID 25416285, 2014). "Interestingly, somatic activating mutations of ErbB2 have very recently been found in some human cancers lacking ErbB2 amplification." (PMID 24709902, 2014). "Thus, the expression of ERBB2, ERBB3 and ERBB4 in EGFR driven cancer may be important to predict the outcome of TKI treatment." (PMID 23758840, 2013). "However, the direct interaction between human MUC4 and ErbB2 has not been proven at this time, moreover, studies on their role in regulating the biological properties of cancer cells have always been carried out separately in different cellular models." (PMID 22393391, 2012).
cancer (continued). "Treatments that stabilize P-eIF2α levels may be effective in treating ErbB2 positive cancers without severely disrupting normal tissue function and structure." (PMID 19754954, 2009). "While it could be shown that vaccination of cancer patients with ErbB2 peptide vaccines can induce or enhance ErbB2-specific immune responses, this did not result in clinical responses." (PMID 15812545, 2005). "Although ERBB2 (HER2) is an established oncogenic driver and therapeutic biomarker in several cancers, current drug approvals do not reflect the diverse spectrum of activating alterations across indications in which HER2-targeted therapies may yield clinical benefit." (PMID 40178042, 2025). "Predicted activation of ERBB2 only in DM is of interest given that DM, and not JDM, is associated with an increased risk of malignancy, and ERBB2 over-expression is also associated with malignancies in numerous cancer types, although this needs further investigation in DM." (PMID 39529136, 2024). "Third, ERBB2 (HER2) mutations were not reported and could be present in a subset of cancers." (PMID 37437231, 2023). "However, ERBB2 fusions have not been systematically described in pan-cancer." (PMID 36276102, 2022). "The epidermal growth factor receptor (EGFR) kinase family consists of four receptors [ErbB1/EGFR, ErbB2/human epidermal growth factor receptor (HER) 2, ErbB3, and ErbB4] that play a crucial role in cell proliferation, differentiation, and motility and may lead to cancer development." (PMID 36045702, 2021). "Notably, the observed plasma ERBB2 CNs were higher in GI compared to non-GI cancers, indicating that they may be more biologically relevant in these disease settings." (PMID 31019892, 2019). "The novel stimulatory mechanism of ErbB2 for its homodimerization and activation by cis-interacting with nectin-4, which mainly leads to the selective activation of the PI3K-AKT signalling pathway, may be involved in the enhanced DNA synthesis of cancer cells in which nectin-4 is upregulated." (PMID 31831814, 2019). "The absolute ERBB2 copy number in plasma was equivalent among Asian and non-Asian gastric (median CN = 4.8 vs. 4.1), lung (median CN 2.8 vs. 2.5), and breast (median CN 3.3 vs. 2.9) cancer patients but higher in Asian CRC patients (median CN 6.6 vs. 2.7; P = 0.146)." (PMID 31019892, 2019). "Therefore, mir-4728 may also have potential in the treatment of cancers with ERK activation despite being ErbB2-negative." (PMID 25950472, 2015). "Thus, ERBB2 amplification could increase cell migration in expansive carcinomas, whereas infiltrative carcinomas, which already have a strong invasive potential, do not acquire additional advantage from ERBB2 amplification." (PMID 19156142, 2009). "Similar to human cancer cell lines, the lack of TSG101 prevented the initiation of ERBB2/neu-induced mammary cancer." (PMID 40624726, 2025). "ERBB2/HER2-positive EBC is not a singular biological entity; instead, it is characterized by heterogeneity of both cancer and immune cell components." (PMID 38546612, 2024). "The same observation was made when transcriptomic distances were correlated with quantitative parameters of treatment response (residual cancer burden [RCB] score) and the relative fraction of ERBB2-non-amplified cells." (PMID 38300710, 2024). "The killing of the ErbB2+ cells was specific, since the murine ErbB2+ MC38 cancer cells were not eliminated." (PMID 36672182, 2023). "No statistical difference was observed in the abundance of VGFR2, PGFRA, FGFR3, ERBB2, NTRK2 and TIE2 among the healthy, non-tumorous (histologically normal) and tumorous livers from cancer patients." (PMID 36890818, 2023). "Given the successful ranking of regimens for HR-positive, ERBB2-negative MBC, we plan to use IT-NMA to rank regimens for other common and extensively studied cancers." (PMID 35416993, 2022).
cancer (continued). "For further analysis, we selected a group of genes to compare the mRNA abundance of these genes in the ERBB2-negative MCF10A normal-like cells and SKBR3 cell line, a well-established cellular model of ERBB2-amplified cancer." (PMID 34535639, 2021). "ECD KD markedly reduced the levels of ErbB2 mRNA but not the levels of EGFR mRNA, even in a cancer cell line with EGFR overexpression." (PMID 33941617, 2021). "These genes include very well-known cancer related oncogenes such as BRAF, ERBB2, AKT1 and PIK3CA with the genes which are not listed in the cancer gene census list of the COSMIC database." (PMID 32998690, 2020). "Among these genes, elevated expression in cancer tissues was observed for MET and ERBB2, but neither of them predicted patient survival." (PMID 32807134, 2020). "Other ERBB-family-receptors (ERBB2, ERBB3, and ERBB4) were barely expressed in basal cancers, whereas non-basal BLCA showed increased mRNA expression of different ERBBs." (PMID 32978523, 2020). "Samples with fusions involving oncogenes, such as EGFR, ERBB2, and RET, showed increased expression of those genes relative to samples without fusions across cancer types." (PMID 29617662, 2018). "In the present study, we focused on the strongly regulated novel gene by EGFR/ErbB2 blockade, PHLDA2 as it has not been investigated before as a target of oncogenic pathways in cancers." (PMID 29861842, 2018). "Unlike the widely studied erbB2 and EGFR in human cancers, there has been relatively less emphasis on erbB3 as a molecular target for cancer treatment." (PMID 24215614, 2013). "Most slides from cancer-free tissue lacked expression of CCND1, CD44, CDH1, EGFR, ERBB2, KIT, keratins, NOTCH1, PAK1, PTGS2, SNAI1, and VIM but showed staining of MUC1, HIF1A, NKX2-1, SFTPC, and STAT3, which were also found in AdCa." (PMID 23028920, 2012). "Thus, although we did not observe the up-regulation of erbB2 at this specific time point (50 days of age), an up-regulation of erbB3 could provide ample access to a binding partner for erbB2 and provide a local environment more prone for cancer development." (PMID 19590682, 2009). "Interval cancers with DBT (vs DM) less frequently had favorable characteristics: estrogen receptor–positive or progesterone receptor–positive (72.3% vs 84.8%, respectively) and ERBB2-negative (79.2% vs 86.2%, respectively)." (PMID 40402477, 2025). "In more detail, it explains heterogeneity in FGFR4 expression both across PAM50 subtypes and in cancer cell lines, but also within HER2E tumors irrespective of ERBB2 status, and may even be potentially informative as a biomarker for FGFR4 inhibitors." (PMID 40044693, 2025). "Therefore, CDK12 amplification is an extremely rare event in cancer, whereas CDK12 amplification is not infrequent in ERBB2‐amplified ILBC." (PMID 38335502, 2024). "Interestingly, we analyzed the expression of a large panel of immunohistochemical markers and only SOX10 was more frequently expressed in ERBB2‐amplified ILBC, a marker that is typically positive in triple‐negative NST and non‐NST carcinomas." (PMID 38335502, 2024). "As the TCGA dataset lacks expression data from normal ovarian tissues, we could not compare ERBB2 and ERBB3 expression between cancer and normal ovarian tissues." (PMID 35740327, 2022). "In addition, the H&E-based ERBB2 predictor, i.e. H&E-ERBB2 score identified patients who were CISH ERBB2 negative but according to the CNN exhibited ERBB2-positive cancer-like tissue morphological features and had unfavorable outcomes." (PMID 33597560, 2021). "The majority of known driver gene amplifications (e.g., EGFR, ERBB2, MET, and MYC) and homozygous deletions (e.g., CDKN2A, PTEN, and RB1) were captured, with 320 RACSs (38%) containing at least one known putative cancer driver gene, in addition to 531 RACSs (62%) without known driver genes." (PMID 27397505, 2016).
cancer (continued). "Moreover, these MaSCs do not express detectable levels of ERBB2/HER2, reminiscent of the triple-negative receptor phenotype that characterizes many basal cancers." (PMID 20346151, 2010). "However, the degradation of ErbB2 induced either by 17-DMAG or by siRNA does not enhance the radiosensitivity of various carcinoma cell lines." (PMID 20502461, 2010). "These cancers express basal/myoepithelial cell markers such as cytokeratins 5/6, 14 and 17 or vimentin but do not express ESR1, progesterone receptor (PRGR) or ERBB2 (triple negative)." (PMID 19007432, 2008). "Historically, EGFR inhibitors have not been effective against KRAS-mutant cancers; however, second generation inhibitors have shown promise in treating both KRAS- and EGFR-mutant tumors by targeting all members of the ErbB family of proteins (EGFR/ERbB1, HER2/ErbB2, HER3/ErbB3, HER4/ErbB4)." (PMID 36674513, 2023). "As expected, we identified a lower proportion of ERBB2-high tumors in each cancer type as compared to standard IHC/ISH definition of HER2-positivity, thus potentially selecting tumors sensitive to T-DM1 treatment even in cancer types generally not considered amenable to treatment with this agent." (PMID 32674482, 2020). "In addition, this case showed carcinoma-specific amplification of 7p (EGFR and BRAF) and 20q (ASXL1, AURKA, and GNAS), which were observed as clonal amplification for the three MSS cases without ERBB2 amplification." (PMID 26336987, 2015).